RNU6-901P (RNA, U6 small nuclear 901, pseudogene)
Gene: Small nuclear RNA gene on chromosome 3 (153,471,466 to 153,471,571, reverse strand). Ensembl gene ENSG00000207323.
Homologues: Orthologues: chimpanzee U6 (98% identical), macaque U6 (89% identical), rat LOC120094860 (78% identical), guinea pig U6 (63% identical). Paralogues in human: RNU6-1060P (90% identical), RNU6-116P (90% identical), RNU6-15P (89% identical), RNU6-19P (88% identical), RNU6-33P (88% identical), RNU6-1 (87% identical), RNU6-12P (87% identical), RNU6-13P (87% identical), RNU6-17P (87% identical), RNU6-18P (87% identical), RNU6-2 (87% identical), RNU6-31P (87% identical), and 1288 more.